JUN (Jun proto-oncogene, AP-1 transcription factor subunit)
Diseases named in the same sentence as JUN in open-access papers (continued):
Sharing a sentence is not in itself a finding about the gene and the disease.
COVID-19 (continued). "A decrease in the expression of the following genes was also observed in COVID-19-positive patients: RAPGEF1 (p = 0.0091), MAP2K1 (p = 0.038), CEBPB (p = 3.3 × 10−6), STAT6 (p = 0.041), JUN (p = 1.4 × 10−8), PRKACA (p = 0.021), and AKT1 (p = 1.3 × 10−6)." (PMID 36298734, 2022). "In the COVID-19 cohort, IL6, PTSG2, JUN, ATF3, SOCS3, CSF3, and NFKB2 had AUC values greater than 0.7." (PMID 36380355, 2022). "JUN is a key regulator of inflammatory cytokine genes, such as CCL2, and is expressed at high levels in COVID-19 patients." (PMID 35639708, 2022). "We screened the genes based on their degree values and identified RELA, BCL2, JUN, FOS, and MAPK1 as possible core target genes for puerarin in treatment of COVID-19/COAD." (PMID 35677450, 2022). "Co-targets were 194 genes intersecting with COVID-19, RA-DEGs (GSE55235), and pyroptosis-related genes, including 7 genes: CASP1, CASP8, IL1B, CASP3, JUN, EGFR, CXCL8." (PMID 36532040, 2022). "In contrast, many TFs were identified specifically as the top TFs in COVID-19 patients’ lung cell types, including SMAD3 in ciliated cells, NFKB1 and JUN in dendritic cells, PPARG in macrophage/monocyte cells, and STAT3 in T cells." (PMID 35458567, 2022). "We identified FOS, NFKB1, JUNB, JUN, and NFKB1A as core target genes of quercetin for the treatment of COAD/COVID-19." (PMID 36249762, 2022). "In individuals with COVID-19, CD4+ T cells expressed significant amounts of inflammatory genes, including JUN." (PMID 37521843, 2022). "Independent prognosis and survival analysis revealed important differential genes, including RACGAP1, TCF7L2, IRF7, DMD, and JUN, which can be used as effective biomarkers for screening and characterizing patients with BRCA and COVID-19 at all stages." (PMID 36060002, 2022). "From 11 healthy cell-type TRNs and 8 COVID-19 cell-type TRNs, we identified 8 unique central TFs, FOXP1, RUNX1, FOS, SMAD3, JUN, NFKB1, PPARG, and STAT3." (PMID 35458567, 2022). "Specifically, JUN and NFKB1 are significantly upregulated in male monocytes with severe COVID-19 compared to females (q < 2.0 × 10−16)." (PMID 34330889, 2021). "By using Cytoscape software to visualize the degree of each gene in the PPI network, we found that RELA, BCL2, JUN, FOS, and MAPK1 had the highest degree, suggesting that the five genes might be core targets of puerarin in COVID-19/COAD comorbidity." (PMID 35677450, 2022). "We hypothesize that RELA, JUN, NF-κB1, NF-κB2, and FOS are the main targets of puerarin in the therapy of EHF/COVID-19 based on protein interactions." (PMID 35663983, 2022). "Furthermore, the downstream factors of TLR7 and BTK in TLR pathway, such as MYD88, IRF7, NFKB1, and JUN, and cytokines (TNF, IL1B, and IL18) were elevated in men with severe COVID-19." (PMID 34330889, 2021). "Notably, our identification of H3-5/H3F3C, H3C13/HIST2H3D, JUN, EGR1, NOTCH1, and SQSTM1/P62 as central hub genes unique to the COVID-19 signature links this pro-oncogenic state to a specific molecular target that regulates inflammation, autophagy, and cancer progression." (PMID 41472277, 2025). "FOS, JUN, NFKB1, JUNB, and NFKB1A had the highest degree values, so we concluded that these genes might be the core target genes of quercetin for the treatment of COAD/COVID-19." (PMID 36249762, 2022). "Furthermore, the roles of other stroke-associated genes, such as SAMHD-1, DDAH-1, HMOX1, LTC4S, ACTB, KPNA2, and JUN, in mediating stroke secondary to SARS-CoV-2 infection are required to be further explored experimental using COVID-19 patient samples or SARS-CoV-2 animal models." (PMID 33732102, 2021). "Notably, the mitogen-activated protein kinase (MAPK) pathway (i.e., FOS, JUN, JUNB, and DUSP1) was greatly suppressed in all recovered patients compared with that in the HCs, which suggested that inhibition of the MAPK signaling pathway is a recovery sign of COVID-19 patient." (PMID 37853311, 2023).
pancreatic cancer (49 papers, 2012 to 2026). "NCBP2 binds to m7G‐modified c‐JUN mRNA and enhances MEK/ERK signaling by upregulating c‐JUN translation, thereby promoting pancreatic cancer growth." (PMID 40448344, 2025). "The activation of PSCs was mediated by pancreatic cancer cells-derived PAI-1 acting through the LRP-1/ERK/c-JUN pathway." (PMID 31695760, 2019). "We demonstrate that VASH2 is overexpressed in human pancreatic cancer and functions as a gemcitabine-resistance factor by Jun proto-oncogene (JUN) dependent transactivation of ribonucleotide reductase regulatory subunit M2 (RRM2)." (PMID 28327155, 2017). "JUN interacts with NR3C2 to modulate glycolysis in pancreatic cancer." (PMID 40332792, 2025). "Heatmap analysis in colorectal, stomach, and pancreas cancer patient datasets showed a consistent overlap between LBH overexpression and WNT signaling genes associated with pathway activation, i.e., WNT2, WNT5A, WNT11, LEF1, TCF4 or TCF7, CCTNB1, CCND1, JUN, DKK3." (PMID 37268816, 2023). "Although there are scientific reports on the prognostic values of SMAD3 and CTNNB1 in pancreatic cancer, the precise functions of Jun Oncogene (JUN) and TCF-7 in the pathogenesis of pancreatic cancer are still largely unknown and require further understanding and research." (PMID 33194391, 2020). "For example, deletion of LATS1/2 in organoids or in a mouse model of pancreatic cancer led to the activation of AP-1 and YAP target genes, where YAP physically interacts with the FOS/JUN complex." (PMID 35883668, 2022). "Moreover, NCBP2 facilitates the translation of c-JUN, a protein that activates the MEK/ERK signaling pathway, thereby promoting the growth and proliferation of pancreatic cancer cells." (PMID 40124611, 2025). "It is noteworthy that transcription factors, such as ETS2, JUN, and ELK1, were upregulated in the KRAS mutated CRC, but not in lung and pancreatic cancers." (PMID 33982211, 2021). "FXR was significantly increased in pancreatic cancer cell lines in comparison to normal pancreatic cells and FXR was found as the regulator of FAK (PTK2, protein tyrosine kinase 2)/c-Jun (JUN, Jun proto-oncogene, AP-1 transcription factor subunit) / MUC4 (mucin 4) signaling pathway." (PMID 31379749, 2019). "Here, we found that VASH2 is expressed at high levels in human pancreatic cancer cells and acts as a gemcitabine-resistance factor, and the expression of RRM2 could be upregulated by VASH2 in a JUN-dependent manner." (PMID 28327155, 2017).
liver cancer (47 papers, 2008 to 2025). An epithelial or non-epithelial malignant neoplasm that arises from the liver. "In summary, this unexpected but unbiased finding reinforces the association between NCOR1/2 and JUN’s capacity to suppress YAP target genes and demonstrates a role in YAP-dependent liver cancer." (PMID 39210147, 2024). "At first glance, this finding seems counterintuitive since deletion of JUN leads to increased survival in a chemically induced liver cancer model which would suggest pro-oncogenic properties of JUN in liver cancer." (PMID 39210147, 2024). "The box plot of differential expression analysis showed that JUN was significantly overexpressed in normal tissues than in liver cancer tissues." (PMID 36091226, 2022). "JUN is also deduced as a ferroptosis suppressor in the Ferroptosis Database, which is based on the study performed on human liver cancer cells." (PMID 35992146, 2022). "The study showed a strong correlation between elevated JUN activity and PR to sorafenib in liver cancer." (PMID 34421602, 2021). "In liver cancer, c-JUN forms a positive feedback loop with pluripotent genes to expedite cancer stemness." (PMID 27894081, 2017). "Our results suggest that c-JUN activates CSCs-related genes in liver cancer stem cells, but more studies are needed to understand the network of MBD3, c-JUN, EMT and CD44." (PMID 27894081, 2017). "Elevated expression of OCT4 and c-JUN was observed in specimens taken from patients with liver cancers." (PMID 29259714, 2017). "Macrophage-derived FN1 promotes the migration of liver cancer cells via the JUN pathway." (PMID 40223922, 2025). "By performing large‐scale drug sensitivity testing of liver cancer‐targeting drugs, combined with transcriptome data and machine learning models, they identified high expression of the c‐JUN protein as a key factor contributing to drug resistance in liver cancer." (PMID 39976163, 2025). "To test whether JUN could suppress YAP-dependent liver cancer, we performed hydrodynamic tail vein injection (HDTVI) in conjunction with a sleeping beauty-based approach to stably express genes in the livers of C57BL/6J wild-type mice." (PMID 39210147, 2024). "Moreover, increased expression of OCT4 and c-JUN was confirmed in specimens from patients with liver cancer, and crosstalk between OCT4 and c-JUN was identified as underlying the tumorigenicity of this cancer." (PMID 38791215, 2024). "Furthermore, our study indicates that c-JUN serves as a potential therapeutic target for liver cancer." (PMID 27894081, 2017). "In addition, our results indicate that c-JUN may serve as a potential target for liver cancer therapy." (PMID 27894081, 2017). "A total of 86 targets of the herbal compound for liver cancer were obtained, mainly five core targets of IL-6, ESR1, JUN, IL1β, and MMP9." (PMID 37680619, 2023). "Cellular-JUN and signal transducer and activator of transcription 3 (STAT3) are critical regulators of liver cancer development and progression." (PMID 34954190, 2022). "Moreover, kaempferol markedly suppresses HepG2 cell proliferation and combats liver cancer by increasing BAX and JUN protein expression and decreasing CDK1 protein levels." (PMID 39221164, 2024). "Consequently, JUN is predicted to regulate PGF expression, potentially promoting the migration of liver cancer cells." (PMID 39484208, 2024). "Previous network pharmacological studies had also found that AR and MYC could play a key role in the process of viral hepatitis, liver cirrhosis, and liver cancer and inhibit the expression of AR, JUN, and MYC, which reduce the occurrence of liver cancer." (PMID 35330838, 2022).
liver cancer (continued). "Although the current results do not indicate that liver cancer cells affect the specific mechanism of JUN gene regulation by ALB binding to FcRn, our findings provide a new strategy to elucidate the mechanism underlying PR." (PMID 34421602, 2021). "Furthermore, our results suggest that expression and activity of the transcription factor c-JUN are increased in iCSCs, and are essential for stemness and CSCs properties, indicating that c-JUN might serve as a target for liver cancer therapy." (PMID 27894081, 2017). "Therefore, we hypothesize that both genes are required to generate liver cancer and that the feedback regulation of OCT4 and c-JUN might be critical for triggering CSCs." (PMID 29259714, 2017). "This work identifies an unexpected FOS-independent role of JUN in buffering oncogenic YAP/TAZ activity at target genes, providing a negative feedback mechanism in liver cancer." (PMID 39210147, 2024).
osteosarcoma (47 papers, 2008 to 2025). A usually aggressive malignant bone-forming mesenchymal neoplasm, predominantly affecting adolescents and young adults. "The JUN gene (target of Sartans) shows a strong association with malignant tumors of the colon, lung, liver, and stomach, as well as osteosarcoma." (PMID 37368467, 2023). "Additionally, five key genes, including CD4, RUNX2, OMD, COL9A3, and JUN, were found to be associated with osteosarcoma progression." (PMID 39324133, 2024). "We demonstrated that the knockdown of ITGB3 increased radiosensitization by promoting osteogenic differentiation and apoptosis through activation of the JNK/c-JUN/RUNX2 pathway in osteosarcoma." (PMID 40410897, 2025). "These western blot findings suggested that ITGB3-KD enhanced osteogenic differentiation in osteosarcoma by activating the JNK/c-JUN pathway, with RUNX2 serving as the major downstream molecule mediating this effect." (PMID 40410897, 2025). "The expression of CD4, OMD, and JUN was decreased in Osteosarcoma cells compared with osteoblasts, whereas RUNX2 and COL9A3 expression was increased." (PMID 36686663, 2022). "Research has shown that inhibiting JUN activity can reduce the invasiveness of osteosarcoma cells." (PMID 38297292, 2024). "Our previous study demonstrated that circTADA2A is able to serve as a competing endogenous RNA to accelerate osteosarcoma development by regulating the c-JUN-mediated signaling pathway and that CircSERPINE2 attenuates osteoarthritis by sponging miR-1271 in chondrocytes." (PMID 35332256, 2022). "Similarly, amplifications of MYC, BRCA2, and a co‐amplification of the region PDGFRA–KIT occurred mostly in recurring tumors (P1, P2, P4, P6, P7, P10), whereas JUN and APC mutations occurred in a single osteosarcoma primary (P1)." (PMID 33963544, 2021). "However, further validation is needed to determine whether the increased osteogenic differentiation in osteosarcoma cells resulting from ITGB3-KD-mediated activation of the JNK/c-JUN/RUNX2 pathway directly regulates apoptosis in osteosarcoma cells." (PMID 40410897, 2025). "Taken together, these findings indicate that ITGB3-KD exerts radiosensitizing effects on osteosarcoma cells by promoting osteogenic differentiation and apoptosis through activation of the JNK/c-JUN/RUNX2 pathway." (PMID 40410897, 2025). "Network pharmacology showed that 251 luteolin against osteosarcoma targets and 8 hub targets including AKT1, ALB, CASP3, IL6, JUN, STAT3, TNF, and VEGFA." (PMID 40066267, 2025). "The findings suggest that ITGB3-KD enhances the radiosensitivity of osteosarcoma cells by promoting osteogenic differentiation and apoptosis via activation of the JNK/c-JUN/RUNX2 signaling pathway." (PMID 40410897, 2025). "Consistent with the network pharmacology results, the RT-PCR experiments showed significant downregulation of JUN, HSP90AA1, HDAC1, and CDK1 expression by TGT, highlighting their potential significance as targets in the anti-osteosarcoma mechanism of TGT." (PMID 38297292, 2024). "For example the presence of pyruvate reduced SaOS-2 human osteosarcoma cell cytotoxicity to PAM by phosphorylation of ERK1/2, GSK3β, AMPK, and c-JUN and HSP60 dephosphorylation, which was primarily attributed to pyruvate scavenging H2O2." (PMID 38785562, 2024). "By suppressing the activities of JUN, HSP90AA1, HDAC1, and CDK1, TGT can impede the growth of osteosarcoma cells." (PMID 38297292, 2024). "JUN is activated JNK dependently and promotes apoptotic cell death in malignant cells including osteosarcoma." (PMID 19077262, 2008). "ERK/JNK and c‐JUN/c‐FOS, as upstream activators of FOXP1, drive osteosarcoma development." (PMID 36772869, 2023).
cervical carcinoma (41 papers, 2010 to 2025). A carcinoma arising from either the exocervical squamous epithelium or the endocervical glandular epithelium. "The current investigation elucidated that CEBPD serves as an upstream regulatory factor for key genes, including MYC, IL6, JUN, RRM2, and VEGFA, all of which have been linked to an unfavorable prognosis in cervical cancer patients." (PMID 38926832, 2024). "A PPIN of 90 genes identified FLT1, IGF2, IRS1, JUN, KDR, ZEB1, TIMP2 (downregulated), and EZH2, SOX2, and MYB (upregulated) in cervical cancer samples when compared with normal samples." (PMID 36879084, 2023). "Consequently, the expression levels of JUN and TSC22D3 in cervical cancer tissues displayed an overall downward trend compared with non-tumor tissues." (PMID 37187896, 2023). "In addition, the expression of four genes, including JUN, TSC22D3, DUOX1, and HELLS, in cervical cancer tissues was verified by qRT-PCR." (PMID 37187896, 2023). "Combined protein–protein interaction network, hub gene screening, and qPCR validation data showed that ERs-related genes (ATF4 and DDIT3) and the downstream apoptotic genes (JUN, FOS, BBC3, and PMAIP1) were potential novel targets of 20(S)-GRh2-inducing cervical cancer cell apoptosis." (PMID 36431966, 2022). "It implies that ERs-related genes (ATF4 and DDIT3) and downstream apoptosis genes (JUN, FOS, BBC3, and PMAIP1) are the potential targets of 20(S)-GRh2 and might be interacting with each other to be involved in the apoptosis induction in cervical cancer cells." (PMID 36431966, 2022). "Finally, using data from The Cancer Genome Atlas (TCGA), we observed that JUN expression significantly correlated with reduced survival in cervical cancer patients, whereas JUND expression did not." (PMID 33303976, 2021).